RN7SL376P (RNA, 7SL, cytoplasmic 376, pseudogene)
Gene: Miscellaneous RNA gene on chromosome 15 (40,615,665 to 40,615,928, reverse strand). Ensembl gene ENSG00000265814.
Homologues: Orthologues: chimpanzee Metazoa_SRP (98% identical), macaque Metazoa_SRP (83% identical), macaque Metazoa_SRP (74% identical). Paralogues in human: Metazoa_SRP (77% identical), RN7SL275P (77% identical), RN7SL744P (75% identical), RN7SL619P (75% identical), RN7SL560P (74% identical), Metazoa_SRP (73% identical), RN7SL470P (70% identical), RN7SL510P (69% identical), RN7SL596P (69% identical), RN7SL391P (69% identical), RN7SL774P (68% identical), RN7SL32P (68% identical), and 702 more.